VIM (vimentin)
Diseases named in the same sentence as VIM in open-access papers (continued):
Sharing a sentence is not in itself a finding about the gene and the disease.
tumor (continued). "SPB was also expressed in cuboidal tumor cells; vimentin was expressed in all polygonal tumor cells and some cuboidal cells." (PMID 25130377, 2014). "Tumour cells were vimentin, synaptophysin, calretinin, inhibin, CD56 and melan A-positive, consistent with the literature." (PMID 24602387, 2014). "Immunohistochemical analysis revealed that the spindle-shaped tumor cells were diffusely reactive to α-actin smooth muscle and vimentin, and focally reactive to desmin." (PMID 24959254, 2014). "Nestin is a stem cell marker expressed by many types of cells during development while vimentin is expressed in mesenchymal cells and involved organogenesis, wound healing and tumor invasion." (PMID 24489858, 2014). "We used a human-specific anti-vimentin antibody and Alu PCR to detect human genomic DNA and both methods confirmed the significantly decreased metastatic burden in knockdown-tumor-bearing mice as compared to control mice." (PMID 24618895, 2014). "Tumors were considered positive when Vimentin expression was detected in more than 10% of the tumor cells." (PMID 24816558, 2014). "The concurrent positive immunostaining for cytokeratin and vimentin indicated mixed epithelial- and mesenchymal-type tumor cells in the malignant neoplasm following surgery." (PMID 25120721, 2014). "The tumour cells demonstrated diffuse positivity for vimentin and patchy nuclear positivity for S100." (PMID 24744936, 2014). "Immunohistochemistry, which was performed by envision method, of tumor showed that the tumor spindle cells were positive for vimentin, CD68, and Ki-67 (labeling = 18%)." (PMID 25379319, 2014). "Cytokeratin and vimentin antibodies staining provided the tumor and stromal masks respectively, and DAPI served to define the nuclear mask." (PMID 25485872, 2014). "Results indicated that Twist1/vimentin expression in carcinoma tissues were higher than adjacent non-tumor tissues, and its expression in middle/low differentiation carcinoma tissues higher than high differentiation tissues." (PMID 25144746, 2014). "Different cytoplasmic proteins are important in the transformation of a normal cell to an invasive tumor cell, and these include vimentin and Notch." (PMID 24527079, 2014). "The tumour cells demonstrated immunopositivity for vimentin and immunonegativity for cytokeratin, epithelial membrane antigen, desmin, myogenin, and smooth muscle actin (SMA)." (PMID 24744936, 2014). "The tumor showed positive staining with antibodies to neuron specific enolase, vimentin, S-100, and GFAP." (PMID 25144312, 2014). "Immunohistochemically, tumor cells showed diffuse positivity for vimentin, CD99 and S100, while focal positivity was seen with pancytokeratin immunostain." (PMID 25395990, 2014). "RCAS1 alters the tumor microenvironment by inducing peripheral lymphocyte apoptosis and angiogenesis, while reducing the vimentin-positive cell population." (PMID 25177692, 2014). "We confirmed the human origin of the tumor in the mouse brain two weeks after inoculation using a specific antibody that recognizes human vimentin." (PMID 25482099, 2014). "Captured cells into collecting reservoir were confirmed to be tumor cells using microscopy of cell morphology and positive CK and vimentin fluorescent labeling, while contaminating cells were identified by cell morphology and positive CD45 staining." (PMID 24886394, 2014). "The immunohistochemical profile was consistent with the one described in AT in usual locations (genital tracts) and was typical for a tumor of mesothelial origin: calretinin (+), CK(cytokeratin) 5/6 (+), CK 7(+), vimentin (+), D2-40 (+), CD31(-) and CD34 (-)." (PMID 25487416, 2014). "Immunohistochemistry was performed to determine the expression of E-cadherin, Vimentin, Snail, slug and β-catenin in a tissue microarray consisting of tumor tissues of 140 ICC patients undergoing curative resection." (PMID 24816558, 2014).
tumor (continued). "Vimentin shows a positive reaction in most cases but it is less specific and can be positive in a variety of other neoplasms." (PMID 24716058, 2014). "Our immunohistochemical analysis revealed that the tumor was positive for Chromogranin A, vimentin, S-100, synaptophysin, thus providing a histopathological basis for a correct diagnosis of nonchromaffin paraganglioma of the retroperitoneum in the patient." (PMID 23537060, 2013). "The tumor cells were positive for vimentin and AAT, which indicated that the tumor was composed of undifferentiated mensenchymal cells." (PMID 24073982, 2013). "Immunohistochemical staining of tumor specimens was used to analyze the protein expression of the epithelial marker E-cadherin and the mesenchymal marker vimentin." (PMID 23520479, 2013). "Immunohistochemically, the tumor cells exhibited diffuse positive immunoreactivity for p63 and perinuclear dot-like positivity for vimentin, leading to a final diagnosis of BSCC of the maxillary sinus." (PMID 23833636, 2013). "We observed Nestin and Vimentin expression in the treatment groups as well as the controls, both in the tumor bulk and the invasion zone." (PMID 24312904, 2013). "Vimentin is also found to be involved in cell growth, cell cycling, and tumour differentiation.Objective." (PMID 23840210, 2013). "Staining of tissues collected 24 h after treatment displayed extensive decrease in E-cadherin and increase in ZEB1 and vimentin in surviving tumor adjacent to the thermal injury compared with control (control and thermal ablation treated)." (PMID 24403226, 2013). "Immunohistochemistry revealed that tumor cells express Vimentin, Bcl-2, and Mic-2 with crisp cytoplasmic positivity suggesting the diagnosis as poorly differentiated small cell variant synovial sarcoma." (PMID 23762651, 2013). "Vimentin has also been described as a tumor-specific angiogenesis marker, and targeting endothelial vimentin in a mouse tumor model significantly inhibited tumor growth and reduced microvessel density." (PMID 23785295, 2013). "Vimentin expression is significantly enhanced in cell growth, cell cycling, tumor differentiation, and during the process of tumorigenesis." (PMID 23840210, 2013). "Vimentin stains most tumor cells and neural markers, such as NSE, and is frequently expressed by tumor cells." (PMID 23537038, 2013). "Immunohistochemistry the tumor was positive for vimentin, focal positivity with AE1-AE3 CK, CK5 and high molecular weight cytokeratin and negative for EMA, CD34, desmin, myosin, CroA, synaptophysin and S100." (PMID 23886403, 2013). "Immunohistochemical findings have revealed that 74% of these tumor are positive for vimentin and 94% positive for S-100 protein, features consistent with neural crest lineage or cartilaginous differentiation." (PMID 23800162, 2013). "Tumor cells are stained with vimentin, (alpha-) smooth muscle actin, and muscle-specific actin with a variable expression of desmin." (PMID 23445571, 2013). "We noticed that the enforced overexpression of miR200c in the CD44+CD117+CSCs significantly reduced the expressions of both ZEB1 and Vimentin, but increased the expression of E-cadherin in the RNA and the protein levels in tumor samples." (PMID 23842108, 2013). "Immunostaining with antibodies against EMT markers that include either the loss of E-cadherin or an increase in vimentin expression, showed a significant increase of EMT following cisplatin treatment in tumour tissues." (PMID 23629957, 2013). "Within an hour of treatment strong upregulation of vimentin staining was seen within the viable tumor rim with both cytoplasmic and nuclear localization clearly prominent (vimentin 1 h treated)." (PMID 24403226, 2013). "The results showed a large decrease in E-cadherin staining and a reciprocal strong increase in the staining of ZEB1 and vimentin compared with control tumor (control and SMA-pirarubicin treated)." (PMID 24403226, 2013).
tumor (continued). "The human tumor-derived stromal cells and the xenograft stroma (host derived) were both vimentin positive." (PMID 24324581, 2013). "Concomitant with down-regulation of E-cadherin was the expression of vimentin, a major cytoskeletal protein ubiquitously expressed in mesenchymal cells and tumor cells undergoing metastasis." (PMID 24146752, 2013). "Immunohistochemical staining showed that the tumor cells were strongly positive for vimentin and CD99, focally positive for neuron specific enolase (NSE) and chromogranin A (CgA), and negative for cytokeratins, CD3, desmin, and leukocyte common antigen (LCA)." (PMID 23537038, 2013). "The haematoxylin and eosin appearances of our case is that of a biphasic tumour with a predominant sarcomatous component focally positive for vimentin and few clusters of epithelial component with CEA and CK7 positivity." (PMID 23476861, 2013). "In mouse tumors, recurrent disease display very intense staining for the mesenchymal marker, Vimentin, compared to primary tumor." (PMID 24403249, 2013). "The tumor cells were positive for pan-Cytokeratin, Vimentin, E-cadherin, CD10, and CK7, confirming the diagnosis as CDC." (PMID 23866935, 2013). "Amongst its target, FMRP controls E-cadherin and Vimentin levels, important molecules for cell adhesive properties, cytoskeleton remodelling and consequently tumour cell behaviour." (PMID 24092663, 2013). "Immunohistochemically, the tumor cells demonstrate positivity for vimentin, MSA, SMA and cytokeratin." (PMID 24294990, 2013). "The overexpression of vimentin is always correlated with tumour growth and invasion, where vimetin is believed to regulate various intracellular signalling and cell cycle control pathways." (PMID 23690850, 2013). "Epithelial to mesenchymal transition (EMT) is characterized by the loss of the epithelial marker E-cadherin, and expression of mesenchymal markers such as N-cadherin and vimentin which is regarded as a critical characteristic of tumor invasion and metastasis." (PMID 23622143, 2013). "It has been reported that vimentin can be targeted for tumor inhibition due to its specific up-regulation in tumor vasculatures." (PMID 23785295, 2013). "Remarkably, some primary cells co-expressed cytokeratin and vimentin filaments, which is often found in injured epithelial cells, tumours and in primary cultures due to the detachment of the cells from their natural environment during isolation." (PMID 23964891, 2013). "Immunohistochemical staining showed that the tumor cells were positive for CK, Vimentin, partly positive for E-cadherin, weakly positive for CD10 and CK7, which was basically consistent with the literature." (PMID 23866935, 2013). "Remarkably, some of the ileum epithelial cells did also express vimentin, resembling dedifferentiated epithelial cells typically found after injury or in tumours." (PMID 23964891, 2013). "Among many proteins present in the tumor microenvironment, E-cadherin and vimentin were shown to be important in cell-to-cell adhesion." (PMID 23840707, 2013). "Immunohistochemically, the tumor was positive for S100 protein, vimentin and neuron-specific enolase labeling." (PMID 23369465, 2013). "Immunohistochemistry revealed that expression of E-cadherin and FMRP were inversely correlated, while FMRP and Vimentin levels were directly correlated in both human and mouse tumour tissues." (PMID 24092663, 2013). "Immunohistochemically, the tumor cells are frequently stained diffusely positive for vimentin and focally positive for EMA, cytokeratin, NSE and S-100." (PMID 23761028, 2013). "Under these conditions, Axl levels were decreased, suggesting that vimentin down-regulation was sufficient to drive tumor cells toward an epithelial state." (PMID 23785295, 2013). "Immunohistochemically, the tumor cells were diffusely positive for vimentin and focally positive (cytoplasmic and dotlike) for neuron-specific enolase (NSE), S-100 and epithelial membrane antigen (EMA)." (PMID 23761028, 2013).
tumor (continued). "Noticeably, the expression of all mesenchymal markers analyzed (N-CAD, TNC, VIM and FN 1) was significantly higher in the tumor cells than in the Nthy.ori 3.1 thyrocytes." (PMID 24069422, 2013). "This strategy utilized the tumor-targeting peptide VNTANST which targets tumor-specific ectopic expression of vimentin." (PMID 24369443, 2013). "Staining for EMT markers revealed a decrease in E-cadherin especially in areas adjacent to necrotic regions and increase in ZEB1 and vimentin compared with control tumor (control and sunitinib treated)." (PMID 24403226, 2013). "Third, immunohistochemical analyses of not merely epithelial markers, including CK5/6 and 34βE12, but CD10 and vimentin were positively expressed in the tumor nests." (PMID 23651662, 2013). "Histologically, the recurrent tumor was composed of the closely packed cells positive for vimentin and S-100 proliferating in a nodular fashion." (PMID 23800162, 2013). "Immunohistochemistry the tumor was positive for vimentin, smooth muscle actin and Ki-67; focal positivity with AE1-AE3 CK, CK5 and high molecular weight cytokeratin and negative for EMA, CD34, desmin, myosin, CroA, synaptophysin and S100." (PMID 23886403, 2013). "To characterize the function of the downregulation of ZEB1, we examined the expression of ZEB1, E-cadherin and Vimentin, respectively, in the tumor tissues of the EOC-bearing nude mice." (PMID 23842108, 2013). "EMT is a crucial event in tumor progression, and it is associated with dysregulation of DICER1, E-cadherin and miR-200 family, and upregulation of vimentin, N-cadherin, Twist1, Snail and Zeb2." (PMID 23680357, 2013). "ZEB1 is expressed by infiltrating cells and some tumor cells and vimentin is also expressed at low levels (control)." (PMID 24403226, 2013). "We found that compared to adjacent normal tissues, Wnt5a-overexpressing tumor tissues had elevated expression of vimentin and reduced expression of E-cadherin, indicating the presence of EMT." (PMID 24156409, 2013). "The results of this study and previous data indicate that VIM is a functional target of tumor suppressive miR-138, and this pathway contributes to cancer cell migration, invasion, and metastasis." (PMID 22766839, 2012). "Immunohistochemically, the tumor cells showed positive for vimentin and CD68, while stains for CK, CK8/18, CD35, CD21, CD1a, S-100, HMB45, MelanA, SMA, LCA were all negative." (PMID 22221822, 2012). "As expected, epithelia in TβRIIfl/fl tumors, marked by cytokeratin 8/18, expressed α-smooth muscle actin and vimentin at the tumor-stromal interface and at the edges of lobular tumor structures, confirming a mesenchymal phenotype." (PMID 22748014, 2012). "Immunohistochemically, the tumor cells showed positive for vimentin, while stains for CK, EMA, Calponin, CD34, AFP, hepatocyte and S-100 were all negative." (PMID 22221822, 2012). "This is based on the roles of CD44 and Oct-4A in defining TICs, on the motility/invasivity of vimentin-rich tumor cells, and on the expression of CAF markers α-SMA and PDGFβ-R." (PMID 22901285, 2012). "Immunohistochemistry (IHC) showed that the majority of tumor cells strongly expressed vimentin but exhibited weak staining of E-cadherin and cytokeratin." (PMID 23049725, 2012). "It had been reported that N-cadherin is crucial for tumor-vessels interactions, extravasation and metastatic dissemination and vimentin is widely used as a marker accounting for the epithelial to mesenchymal transition (EMT)." (PMID 22470568, 2012). "Based upon its affinity for vimentin, it has been proposed that WFA can be used as an anti-tumor agent to target metastatic cells which up-regulate vimentin expression." (PMID 22720028, 2012). "In some tumor areas, cells with either Vimentin or E-cadherin expression were observed in close proximity." (PMID 23050024, 2012).
tumor (continued). "Immunohistochemically, the tumor cells were widely positive for vimentin, CD56, CD99 and focally positive for synaptophysin, CD10, progesterone receptor, desmin and CD34, but negative for EMA, cytokeratin, estrogen receptor, S-100 and myoglobin." (PMID 23217062, 2012). "On the other hand, Vimentin overexpression in cancer tissues also correlates with tumor growth, tumor invasion, and poor clinical outcome." (PMID 23076115, 2012). "Paraffin sections were stained with human-specific anti-vimentin antibody to enhance the contrast between tumor cells (brown) and host brain (blue counterstain)." (PMID 22583806, 2012). "Our results show that Wnt signaling upregulates EMT-related molecules Vimentin and β-catenin and increased tumor cell migration and invasion." (PMID 22606268, 2012). "The most sensitive myogenic markers were vimentin and calponin (positive in 93.8% of our cases), but these antibodies have little specificity, as they are also expressed in tumours showing smooth muscle or myofibroblastic differentiation." (PMID 22452794, 2012). "The spindle cell component expressed vimentin (Dako), desmin (Invitrogen, Camarillo, CA) in 10% of tumour cells, and myogenin (Dako) in 10% of tumour cells indicating partial rhabdomyosarcoma-like differentiation, EGFR (Invitrogen), and CD56 (Invitrogen)." (PMID 23006472, 2012). "Taken together, our results suggest that both re-induction of E-cadherin expression and downregulation of vimentin expression contribute to tumor growth inhibition resulting from N-cadherin silencing in Ep5ExTu cells." (PMID 23216791, 2012). "Histological analysis of tumor sections isolated at day 10 post injection confirmed the re-expression of E-cadherin and downregulation of vimentin in Sh-Ncad2 tumors in vivo." (PMID 23216791, 2012). "Immunohistochemical analysis of transplanted tumour suggests that such 81B-Fb cells are originated from E-cadherin(−)/vimentin(+) tumour cells present at the invasion front of UMSCC81B-GR3 tumour tissue." (PMID 22315058, 2012). "Immunohistochemical studies revealed that tumor cells were stained immunohistochemically for CK, VIM, and Calponin protein." (PMID 23236991, 2012). "Under these conditions, EMT is defined as the occurrence of a variable proportion of tumor cells that express mesenchymal markers, such as vimentin and tenascin." (PMID 23110550, 2012). "Immunohistochemically, the tumor cells were widely positive for vimentin, CD56, CD99 and focally positive for synaptophysin, CD10, progesterone receptor, desmin and CD34, but negative for EMA, cytokeratin, estrogen receptor, S-100, GFAP and myoglobin." (PMID 23217062, 2012). "There was a significant increase in the proportion of Vimentin expressing tumor cells and significant decrease in the proportion of E-Cadherin expressing tumor cells in regressed tumors compared to tumors from vehicle-treated mice." (PMID 23115623, 2012). "Snail is known to downregulate the expression of E-cadherin and cytokeratin 18 and to upregulate the expression of vimentin and thus its expression leads to a mesenchymal phenotype of the tumor cells while the cohesion of the cells at the same time decreases." (PMID 23157169, 2012). "Vimentin staining was slightly more intense in the periphery where the occasional tumor cell also displayed nuclear staining (arrows indicate nuclear vimentin)." (PMID 23153292, 2012). "Similar to Primary Tumor Focus #6, the chest wall recurrence contained solid sheets of malignant cells that were positive for vimentin, CK5, and CK8/18, but E-cadherin staining was notably less intense (third row)." (PMID 23049838, 2012). "Both sphere- and adherent culture- generated xenografts highly resembled the patient tumor, as indicated by hematoxylin and eosin staining, expression of the LMS diagnostic marker Smooth Muscle Actin (SMA), caldesmon, HHF35 and vimentin." (PMID 23056514, 2012).